FUT4 (fucosyltransferase 4)
Diseases named in the same sentence as FUT4 in open-access papers (continued):
Sharing a sentence is not in itself a finding about the gene and the disease.
endometriosis (11 papers, 2014 to 2025). The growth of functional endometrial tissue in anatomic sites outside the uterine body. "Elevated FUT4 mRNA levels are significantly associated with endometriosis and correlate with disease severity." (PMID 41009445, 2025). "In future research, a pathogenic role of FUT4 in endometriosis awaits extensive investigation." (PMID 36233470, 2022). "However, the levels may also be explained by increased expression of the FUT4 gene in endometriosis-associated SSEA-1+ epithelial glandular cells." (PMID 36233470, 2022). "The test involves taking a swab from the uterine cavity and determining the expression level of the gene encoding the protein fucosyltransferase 4 FUT4, which is significantly higher in patients with endometriosis." (PMID 39526567, 2025). "Evaluation of FUT4 mRNA for the diagnosis of endometriosis fulfills the criteria of high accuracy, sensitivity and specificity with high positive and negative prediction values." (PMID 36233470, 2022). "This study is the first to present data showing that FUT4 mRNA levels are significantly upregulated in the eutopic endometrium of patients with endometriosis when compared to the endometrium of healthy control women." (PMID 36233470, 2022). "qRT-PCR analysis revealed that the relative FUT4 mRNA expression was significantly higher in eutopic endometrium samples from women with endometriosis compared to the control group (p < 0.0001)." (PMID 36233470, 2022). "The expression of FUT4 mRNA was significantly increased in the endometrium of patients with endometriosis when compared to the controls (p < 0.0001)." (PMID 36233470, 2022). "The results of the present study show that the expression of FUT4 mRNA in the endometrium of patients with endometriosis is significantly increased when compared to healthy women." (PMID 36233470, 2022). "It is plausible that higher levels of FUT4 mRNA in the eutopic endometriosis tissue simply reflect the persistence of increased numbers of SSEA-1+ precursor/stem cells." (PMID 36233470, 2022). "FUT4 mRNA levels were examined in 49 women with laparoscopically confirmed endometriosis and 28 controls by means of quantitative reverse-transcription polymerase chain reaction (qRT-PCR)." (PMID 36233470, 2022). "ROC analysis confirmed that the expression of FUT4 mRNA in the eutopic endometrium is a specific marker of endometriosis." (PMID 36233470, 2022). "The relative levels of FUT4 mRNA expression in eutopic endometrium samples from the control group and women with endometriosis were compared and analyzed with regard to the phase of the menstrual cycle, the stage of disease and the lesion localization." (PMID 36233470, 2022). "Of particular interest, was the observation that in women with endometriosis, SSEA1+ epithelial cells had significantly elevated levels of FUT4 compared with SSEA1+ epithelial cells from healthy women without endometriosis." (PMID 30496412, 2019). "The test, evaluated using qRT-PCR, demonstrates high accuracy (AUC = 0.90) in distinguishing women with endometriosis from controls, suggesting that FUT4 expression could serve as a specific molecular marker for the condition." (PMID 41009445, 2025). "Therefore, the present study was aimed at comparing the expression of specific FUT4 mRNA in the endometrium of control women and women with endometriosis." (PMID 36233470, 2022). "ROC analysis revealed that the expression of FUT4 mRNA in samples of the eutopic endometrium could serve as a suitable marker for the minimally invasive diagnosis of endometriosis." (PMID 36233470, 2022). "This may support the role of FUT4 activity and FUT4-mediated glycosylation in the etiopathogenesis of endometriosis." (PMID 36233470, 2022). "These factors are considered to play a part in the etiopathogenesis of endometriosis; therefore, it is plausible that they may contribute to increased expression of FUT4 mRNA in the endometrium of women suffering from endometriosis." (PMID 36233470, 2022).
endometriosis (continued). "Therefore, the evaluation of FUT4 mRNA appears to be a suitable method for a minimally invasive diagnosis of endometriosis." (PMID 36233470, 2022). "Therefore, FUT4 mRNA from the endometrium may serve as a specific marker that can be used to diagnose endometriosis in a minimally invasive manner." (PMID 36233470, 2022). "Although endometriosis appears to be associated with increased numbers of SSEA-1/SLeX+ cells in the eutopic endometrium, it is highly plausible that this phenomenon may be related to the upregulated expression of the FUT4 gene." (PMID 36233470, 2022). "However, it is intriguing to speculate that, in addition to being a marker of endometriosis, overexpression of FUT4 may play an important role in the development and persistence of endometriotic lesions." (PMID 36233470, 2022). "Thus, increased FUT4 expression in SSEA1+ cells in endometrial epithelial cells from endometriosis patients could similarly enhance their adhesive nature at ectopic sites." (PMID 30496412, 2019). "Furthermore, it appears that FUT4-mediated fucosylation may play an important role in the development and persistence of endometriotic lesions and, therefore, may be considered a target for endometriosis therapies." (PMID 36233470, 2022). "The discriminatory ability of FUT4 mRNA expression was evaluated by receiver-operating characteristics (ROC), which showed high statistical significance (AUC = 0.90, p < 0.0001), thus indicating that an increased level of endometrial FUT4 mRNA may serve as a specific marker for endometriosis." (PMID 36233470, 2022). "mRNA for FUT4, was upregulated in SSEA1+ cells from women with endometriosis compared with those from normal endometrium." (PMID 30496412, 2019). "To further understand the increased SSEA-1 immunostaining in endometriosis tissues, we assessed several fucosyl transferase enzymes (FUT3, FUT4) to determine if these differed." (PMID 30496412, 2019). "In the present study, we did not discover any significant difference in FUT4 mRNA expression in the endometrium when comparing control women to women with endometriosis in the mid-proliferating and mid-secretory phase." (PMID 36233470, 2022). "Increased expression of FUT4 mRNA in endometriosis was observed irrespective of the lesion type or location." (PMID 36233470, 2022). "Localization of endometriotic lesions (ovarian, peritoneal or both) had no impact on the expression of FUT4 mRNA in the endometrium of women with endometriosis." (PMID 36233470, 2022). "The transcript for FUT3 and FUT4 used as a surrogate for SSEA1 epitope did not change in the endometrial tissue derived from women with endometriosis (n = 6) compared with the healthy fertile control samples (n = 3)." (PMID 30496412, 2019). "Therefore, this study aimed to evaluate the specific expression of FUT4 mRNA in biopsies of the endometrium from women with and without endometriosis." (PMID 36233470, 2022).
ovarian carcinoma (11 papers, 2011 to 2026). A malignant neoplasm originating from the surface ovarian epithelium. "In this study, we evaluated carbon nanotubes (CNTs) bioconjugated with a peptide derived from tumor-associated antigen fucosyltransferase 4 (FUT4) as an immunomodulating platform in an immunocompetent ovarian cancer mouse model." (PMID 42238569, 2026). "FUT4 expression was confirmed in the ID8-Defb29/Vegf-a (ID8DVLuc) ovarian cancer model using flow cytometry and confocal microscopy." (PMID 42238569, 2026). "Based on these findings, we propose that FUT4 peptide-conjugated CNTs function as an antigen-based nanoplatform that enhances antitumor immune responses in a murine ovarian cancer model." (PMID 42238569, 2026). "α3/4-Fucosyltransferases (FUT3, FUT4 and FUT9) are active in ovarian cancer development." (PMID 36231102, 2022).
acute myeloid leukemia (10 papers, 2014 to 2025). Acute myeloid leukemia (AML) is a group of neoplasms arising from precursor cells committed to the myeloid cell-line differentiation. "For instance, the Wnt/β-catenin pathway is regulated by the miR-29b/Sp1/FUT4 pathway, which controls acute myeloid leukemia (AML)." (PMID 38343056, 2024).
breast tumor (6 papers, 2015 to 2025). "FUT4 is an enzyme responsible for abnormal fucosylation in cancer cells, associated with the proliferation and metastasis of breast tumour cells, and it is also suggested as a biomarker for the diagnosis of breast tumours." (PMID 31374984, 2019).
mesothelioma (6 papers, 2006 to 2022). A usually malignant and aggressive neoplasm of the mesothelium which is often associated with exposure to asbestos. "The genes FUT4 and ST6GALNAC3 coding for CD15 and Sialyl Transferase that are negative markers of mesothelioma, were down-regulated." (PMID 19662092, 2009).
multiple myeloma (6 papers, 2010 to 2025). "In our previous study (PMID: 34671604), we found that miR-317b-5b not only exerted anti-tumor effect, but also downregulated FUT4 expression in human myeloma cell line 143B." (PMID 40302797, 2025). "LncRNAHOXB-AS1 controls AML through ELAVL1 and encourages the proliferation of multiple myeloma cells through the stability of FUT4 mRNA." (PMID 38343056, 2024). "Specifically, lncRNA HOXB-AS1 has been testified to recruit ELAVL1 and thereby maintain FUT4 mRNA stability in multiple myeloma." (PMID 34911544, 2021). "In addition, in a prior investigation, we discovered that human myeloma cells 143B cultured with modified exosomes loaded with miR-371b-5p had lower FUT4 levels than controls." (PMID 38343056, 2024).
osteosarcoma (6 papers, 2017 to 2025). A usually aggressive malignant bone-forming mesenchymal neoplasm, predominantly affecting adolescents and young adults. "To further understand the molecular functions and consequences of miR-371b-5p/FUT4 on osteosarcoma, we conducted a variety of rescue experiments." (PMID 40302797, 2025). "Osteosarcoma cells exhibit down-regulation of miR-371b-5p, that prevents osteosarcoma cells from proliferating, invading and migrating in order to promote osteosarcoma cell apoptosis through concentrating on the breakdown of FUT4." (PMID 40302797, 2025). "Current research has indicated that both miR-371b-5p and FUT4 play regulatory roles in osteosarcoma cells, and miR-371b-5p has also been found to affect the expression level of FUT4 in osteosarcoma cells." (PMID 40302797, 2025). "This study aims to investigate the biological function of miR-371b-5p in osteosarcoma progression and the role of FUT4 in this process." (PMID 40302797, 2025). "Through bioinformatics analysis and cellular experiments, we aim to study the interaction between miR-371b-5p and FUT4, and further investigate the regulatory role of miR-371b-5p/FUT4 in osteosarcoma cells." (PMID 40302797, 2025). "The correlations between miR-371b-5p, its downstream gene FUT4 and its potential mechanisms in mediating osteosarcoma progression were explored with the assistance of dual-luciferase reporter analysis together with rescue experiments." (PMID 40302797, 2025). "Si-FUT4 considerably reduced the invasion and migration of human osteosarcoma cells, according to the results of the transwell experiment." (PMID 38343056, 2024). "We first assessed the levels of FUT4 expression in osteoblasts and osteosarcoma cells in this study." (PMID 38343056, 2024). "Fucosyltransferase 4 (FUT4) is known to play a role in osteosarcoma cell proliferation and metastasis." (PMID 38343056, 2024). "Further EdU analysis revealed that si-FUT4 transfected human osteosarcoma cells had a substantial reduction in proliferation." (PMID 38343056, 2024). "According to the results of a wound healing experiment, si- FUT4 dramatically reduced the migration of human osteosarcoma cells." (PMID 38343056, 2024). "Results from CCK-8 demonstrated that si-FUT4 drastically reduced the viability of human osteosarcoma cells." (PMID 38343056, 2024). "The results showed that osteosarcoma cells expressed more FUT4 than osteoblasts, potentially implicating FUT4 in the emergence of osteosarcoma." (PMID 38343056, 2024). "The osteosarcoma cells' capacities to proliferate, invade, and migrate were markedly inhibited by the inhibition of FUT4 expression, which also increased osteosarcoma cell apoptosis." (PMID 38343056, 2024). "Si- FUT4 dramatically decreased the growth of human osteosarcoma cells, according to a colony formation experiment." (PMID 38343056, 2024). "Inhibition of FUT4 expression in this study restrained the Wnt/β-catenin signaling pathway and hence the osteosarcoma cells' capacities to proliferate, invade and migrate, which is consistent with earlier results." (PMID 38343056, 2024). "By using the CCK-8 assay, colony assay, EDU assay, wound healing assay and Transwell assay, osteosarcoma cells' ability to proliferate, migrate and invade were examined in relation to si- FUT4." (PMID 38343056, 2024). "Inhibiting FUT4 expression greatly accelerated apoptosis in human osteosarcoma cells, according to the TUNEL assay's findings." (PMID 38343056, 2024). "The findings of the current study demonstrated that inhibiting FUT4 expression significantly reduced the abilities to proliferate, invade and migrate osteosarcoma cells while favoring osteosarcoma cell death." (PMID 38343056, 2024). "Osteosarcoma cells are prevented from proliferating, invading, or migrating when FUT4 expression is inhibited." (PMID 38343056, 2024). "We thus put up the following hypothesis about FUT4's potential role in the growth and evolution of osteosarcoma." (PMID 40302797, 2025).
osteosarcoma (continued). "Additionally, in terms of QRT-PCR assay and Western blot assay, miR-371b-5p adversely influenced the relative level of FUT4 in osteosarcoma cells." (PMID 40302797, 2025). "The goal is to initially validate the hypothesis that "miR-371b-5p regulates FUT4 to affect the progression of osteosarcoma"." (PMID 40302797, 2025). "However, the mutual regulatory relationship and mechanism between miR-371b-5p and FUT4 in osteosarcoma still require further investigation." (PMID 40302797, 2025). "Additionally, overexpression of FUT4 induced osteosarcoma cell apoptosis and partially overcame miR-371b-5p's inhibitory effects on osteosarcoma cell's abilities to proliferate, invade and migrate." (PMID 40302797, 2025). "Notably, overexpression of FUT4 largely overrode miR-371b-5p's reduction of osteosarcoma cell's ability to proliferate, migrate and invade as well as its augmentation of apoptosis." (PMID 40302797, 2025). "The Wnt/β-catenin signaling pathway has a significant effect on osteosarcoma cell death, and inhibition of FUT4 expression may target FOXO1 activation to decrease osteosarcoma cells' ability to proliferate, invade, and migrate." (PMID 38343056, 2024). "In comparison with osteoblasts, osteosarcoma cells expressed more FUT4." (PMID 38343056, 2024). "This research suggests that FUT4 regulates Wnt/β-catenin signaling to affect osteosarcoma cells." (PMID 38343056, 2024). "FUT4 plays a crucial role in the progression of osteosarcoma." (PMID 38343056, 2024). "Thus, miR-371b-5p exerts a regulatory role in osteosarcoma through the downregulation of FUT4." (PMID 40302797, 2025). "However, the function and molecular processes of osteosarcoma, as well as the expression of FUT4 in osteosarcoma cells, remain unclear and still require additional research." (PMID 38343056, 2024). "Similarly, estrogen is also a FUT4 modulator and has been described to affect osteosarcoma growth." (PMID 38343056, 2024). "It has been reported that inhibition of Fucosyltransferase4 (FUT4) to activate Forkhead box O1 (FOXO1) can lead to apoptosis of cancer cells, however, the mechanism in osteosarcoma is still unclear." (PMID 38343056, 2024). "Investigating the biological role and probable mechanism of the connection between FUT4 and FOXO1 in the development of osteosarcoma was the aim of this investigation." (PMID 38343056, 2024). "Findings from qRT-PCR assay and western blot assay displayed that human osteosarcoma cells KHOS, SaOS2, U2OS, and 143B expressed more FUT4 than the osteoblast cell line (hFOB1.19)." (PMID 38343056, 2024). "We hypothesize that there could be some interaction between FUT4 and FOXO1, which is crucial for osteosarcoma growth and metastasis." (PMID 38343056, 2024). "Nevertheless, the mechanism behind how FUT4 and FOXO1 interact in osteosarcoma is unknown and requires more research." (PMID 38343056, 2024).
psoriasis (5 papers, 2014 to 2024). An autoimmune condition characterized by red, well-delineated plaques with silvery scales that are usually on the extensor surfaces and scalp. "Furthermore, a comparison of the levels of the enzymes in AD vs psoriatic epidermis suggested a degree of disease-specificity, with B4GALT1, FUT4 and ST6GAL1 found expressed at levels significantly higher than in psoriasis." (PMID 35784319, 2022).
cholangiocarcinoma (4 papers, 2020 to 2022). A carcinoma that arises from the intrahepatic biliary tree (intrahepatic cholangiocarcinoma) or from the junction, or adjacent to the junction, of the right and left hepatic ducts (hilar cholangiocarcinoma). "Our analysis suggests that expression of DEPDC1, FUT4, MDK, PACS1, PIWIL4, miR-22, miR-551b, and DNA methylation of cg27362525 and cg26597242 could be explored further as potential biomarkers of cholangiocarcinoma." (PMID 33193605, 2020).
Infertility (4 papers, 2021 to 2024). "Together, miR-200c and FUT4 may serve as potential markers of endometrial receptivity as well as useful diagnostic and therapeutic targets for infertility." (PMID 39062484, 2024). "The increased expression level of FUT4 was found in the secretory phase as compared with that in the proliferative phase, and decreased level of FUT4 expression was detected in the serum of infertility patients." (PMID 37798282, 2023). "The α1,3-fucosylation of MEST by FUT4 may serve as a new biomarker for evaluating the functional state of pregnancy, and a target for infertility treatment." (PMID 37798282, 2023). "The results of ROC curve analysis showed that the determination of seminal plasma parameters: CLU, FUT3, and FUT4 concentrations may be helpful in the differentiation of infertile groups of patients with both normal and abnormal seminal parameters." (PMID 34341430, 2021). "Women with infertility and miscarriage had lower serum FUT4 levels than healthy non-pregnant and early-pregnancy women." (PMID 39062484, 2024). "ROC curve analysis for examined by us serum parameters revealed that CLU and FUT4 concentrations and relative reactivity of serum CLU glycans with UEA and LCA may be useful in the differentiation of groups of infertile men with abnormal and normal semen parameters." (PMID 34341430, 2021).
metastatic colorectal cancer (4 papers, 2015 to 2020). "Importantly, cancer-related CD15/FUT4 is overexpressed in most of metastatic colorectal cancer (mCRC) patients and participates in cetuximab or bevacizumab mechanisms of resistance in mCRC patients." (PMID 32209115, 2020).
chronic gastritis (3 papers, 2017 to 2025). Inflammation of the stomach that is chronic in nature. "FUT4 catalyzes the formation of type II Lewis antigens and is highly expressed in GC tissues and serum compared with chronic gastritis and gastric ulcer." (PMID 31831855, 2020).
metastatic tumor (3 papers, 2015 to 2025). "In conclusion, cancer-related CD15/FUT4 overexpression is associated with decreased benefit to target and chemotherapeutic agents in metastatic tumors." (PMID 26427914, 2015). "The present study documented the higher mRNA levels of FUT4, FUT5, and FUT8 in advanced stage and metastatic tumor which highlights their role as valuable indicators of aggressiveness and metastatic potential of the disease." (PMID 34703796, 2021). "CD15/FUT4 acts as a downstream regulator of MAPK-ERK pathway independently of EGFR or VEGF pathway, by coupling mitogenic signaling cascade and immune-escape mechanisms of metastatic tumors." (PMID 26427914, 2015).